GSK3B (glycogen synthase kinase 3 beta)
Diseases named in the same sentence as GSK3B in open-access papers (continued):
Sharing a sentence is not in itself a finding about the gene and the disease.
tumor (continued). "The results of the network prediction indicate that ESR2, PIK3CG and GSK3β might be the key targets of ISL against CRC, which was verified by molecular docking, and that its anti-tumour mechanisms might be related to the oestrogen and PI3K/AKT signalling pathway." (PMID 38256877, 2023). "Furthermore, an animal xenograft model demonstrated that DIM combined with 5-Fu considerably reduced tumor growth without any toxic effects by regulating the Akt/GSK-3β and β-catenin levels." (PMID 36785670, 2023). "Our results showed that TGFβRI and GSK3β are located upstream of NDRG1 in the signaling pathway and demonstrated that a combination of TGFβ and GSK3β inhibitors has the potential to reduce TNBC progression by impairing tumor initiation and ALDH1+ and CD44high/CD24- populations of CSCs." (PMID 36594086, 2023). "Since we observed increased phosphorylation of GSK3β at position Ser9, this, as well as the phosphorylation of Akt and mTOR already discussed, suggests an escape mechanism of the treated GBM cells, which ultimately promotes tumor cell survival even upon TMZ+AT101/AT101 therapy." (PMID 37240419, 2023). "Furthermore, peiminine mediates cell cycle arrest by inhibiting Akt/glycogen synthase kinase 3 beta (GSk3β) and AMP-activated protein kinase (AMPK)/autophagy-activating kinase (ULK1) signaling, which leads to reduced autophagic flux, thereby slowing tumor growth down." (PMID 36532788, 2022). "Consistently, GSK-3β knockout or in vivo inhibition in mice results in decreased PD-1 expression in CD8 T cells; increased expression of T-bet, granzyme B, and IFN-γ; enhanced CTL function ex vivo; increased tumor infiltration; and reverted T cell exhaustion in an LCMV model." (PMID 35911672, 2022). "Thus, the increased activity of Gsk3β in TKO mice might explain the delayed time to tumor development and further implies PIM kinases play a role in the Gsk3β pathway." (PMID 35892829, 2022). "However, GSK-3β could also display a tumor-enhancing role, as it has been reported that it promotes NF-κB binding to target genes (e.g., XIAP, BCL2), given that in CLL cells GSK-3β accumulates in the nucleus." (PMID 35681507, 2022). "Mechanism analysis revealed that TROAP silence could significantly downregulate the level of downstream target genes of PI3K/Akt/GSK-3β signaling, confirming that TROAP-induced malignant biological behavior and tumor progression via PI3K/Akt/GSK-3 signaling pathway." (PMID 36419876, 2022). "Considering the ambiguous role of GSK3β activity in cancer, the fact that AZD5363 allows sensitization to doxorubicin while relieving GSK3β of inhibitory post‐translational modification allows us to surmise that, in our context, this kinase acts as a tumor suppressor." (PMID 33338300, 2021). "Therefore, the ABZ-mediated inhibition of tumor migration and invasion via the AKT/GSK-3β/Snail pathway may only be applicable to certain types of tumors." (PMID 34966427, 2021). "The targeting of the GSK-3β isoform alone also provided a tumor suppressive effect, but the mechanism behind this may not be the same." (PMID 34142056, 2021). "It was recently shown that c-Met inhibition by tivantinib/capmatinib reduces GSK3B-mediated PDL-1 degradation, resulting in increased PDL-1 expression and inactivation of co-cultured T cells in the HCC cell line, as well as reduced anti-tumor activity of T cells in mouse models." (PMID 33919277, 2021). "In addition to the directly regulatory mechanism of HIP1R-mediated PD-L1 autophagic degradation, SA-49 activates PKCα/GSK3β/MITF pathway-mediated lysosome biogenesis, leading to PD-L1 autophagic degradation; consequently this enhances T cell activity and inhibits tumor growth." (PMID 33159034, 2020). "Whilst our emphasis has been on the Akt-GSK-3β pathway, it is also possible that other kinases may facilitate the phosphorylation of GATA3, given the signalling intricacies of tumour cells, with PKA and p38 MAPK both previously identified as facilitating GATA3 phosphorylation." (PMID 33298139, 2020).
tumor (continued). "Inhibition of Erk1/2, tyrosine kinase, and/or GSK-3β was implied to be involved in the enhancement of the PI3K-AKT signaling pathway in the undifferentiated cells, resulting in the sustained stemness, and subsequent conversion of miPSCs into CSCs in the tumor microenvironment." (PMID 32572057, 2020). "However, this study did not measure the basal levels of expression and/or activity of GSK3β in the tumor cells, nor did it investigate the direct effects of GSK3β inhibition on tumor cell survival, proliferation and apoptosis." (PMID 32678196, 2020). "However, no studies to date have shown that GSK3β inhibits EMT in tumor cells and attenuates their ability to invade." (PMID 32503133, 2020). "Furthermore, MYH9 expression restored the signals suppressed by FOXO1, including downregulation of GSK3β protein; however, it did not recover mRNA expression or stimulation of β-catenin and its downstream tumor stemness and EMT signals." (PMID 31754475, 2019). "In cancer, much focus has been placed on the role of GSK-3β in tumor progression and modulation of oncogenes (beta-catenin, cyclin D1, and c-MYC), cell cycle regulators (e.g., p27Kip1), and mediators of epithelial-mesenchymal transition (e.g., snail) by GSK-3β have been described." (PMID 29383130, 2017). "Therefore, we suggest that the integrin β3-Akt-GSK3β signaling axis plays an important role in non-canonical TGFβ signaling, determining the invasive properties of tumor cells chronically exposed to TGFβ." (PMID 27015122, 2016). "In this study, overexpression of GSK-3β dramatically down regulates HIF-1α protein expression as well as VEGF mRNA levels, Thus, HIF-1α/VEGF pathway may be involved in transmitting the biological effects of GSK-3β- inhibited tumor growth and angiogenesis." (PMID 26388612, 2015). "Inactivation of GSK-3β and downregulation of ΔNp63 by wogonin enhances apoptosis effect in human nasopharyngeal carcinoma cells through.Wogonin inhibits tumor angiogenesis via degradation of HIF-1α protein in four human tumor cell lines, including MCF-7, MDA-MB-231, HepG2, and HCT116." (PMID 24786691, 2014). "This crosstalk from MAPKs to β-catenin appears to be mediated through the phosphorylation of GSK3β and potentially by the ERK-mediated activation of the ribosomal proteins p70 S6 (officially known as RPS6KB2) and p90 RSK (officially known as RPS6KA1), as described in a variety of tumour cells." (PMID 24816560, 2014). "To determine whether activation of Wnt signaling could induce osteogenic differentiation of tumor stromal cells, we treated CD14-negative stromal cells grown in osteogenic media with the GSK3β inhibitor SB415286, which activates β-catenin and up-regulates canonical Wnt signaling." (PMID 23922683, 2013). "Thus, it appears that ILK is more likely to regulate GSK3β activity directly in vivo, and dysregulation of this nexus, rather than PKB, might have an important role in epithelial-derived tumour growth and survival." (PMID 12771992, 2003). "While GSK-3β inhibition during the priming phase may enhance dendritic cell activation, cross-presentation, and primary CD8 T-cell effector responses to improve early tumor control, sustained inhibition may be detrimental to the development and maintenance of memory T cells." (PMID 40649856, 2025). "Indeed, the study results presented here demonstrated that simultaneous inhibition of integrin αv, STAT3, and GSK3β using cilengitide, WP1066, and AR-A014418, respectively, synergizes with anti–PD-1 therapy and offers a complete tumor regression in about 50% of GBM tumor–bearing mice." (PMID 40131864, 2025).
tumor (continued). "However, sh-DNMT1 tumor-bearing mice exhibited a slightly greater level of p-GSK3β than nontreated xenografted mice, suggesting that glycogen depredation in sh-DNMT1 tumors themselves may also trigger compensatory liver glycogen metabolism to a certain extent." (PMID 38755637, 2024). "The activation of GSK3β and decrease of GPX4 expression induced by CO were also not observed after NAC treatment, indicating that ROS might be the primary cause of tumor-cell ferroptosis in response to CO treatment." (PMID 38263152, 2024). "Therefore, the antitumoral effects of MTX might not be limited to its antiproliferative action on tumor cells but may also result from its ability to “reeducate” macrophages, an effect dependent on the GSK3β-MAF axis." (PMID 36380627, 2023). "Thus, in addition to tumor cell intrinsic C/EBPδ and COX-2, it is conceivable that the tumor microenvironment could also be a source of PGE2 or other signaling pathways that may promote E-cadherin adhesions through inhibition of GSK3β." (PMID 36757813, 2023). "Since miRs function as tumor suppressors depending on their target gene, we further explored this aspect with an miR target prediction tool, and identified the miR-135b-5p site on the 3′UTR region of GSK3β, which suggests that GSK3β may be a target gene for miR-135b-5P." (PMID 33671112, 2021). "Furthermore, ex vivo analysis of dissected tumour samples revealed that the expression of E-Cadherin and GnT-III, in addition with the phosphorylation of JNK and c-Jun was enhanced, while the phosphorylation of AKT and GSK-3β and the expression of N-Cadherin and Snail were reduced." (PMID 32719549, 2020). "In addition, western blot analysis in SMAP-treated tumors detected the simultaneous decrease in Akt/GSK3β/CyclinD1 signaling and ERK phosphorylation levels, suggesting that SMAP induces PP2A-dependent inhibition of these signaling pathways resulting in suppression of tumor growth." (PMID 33275593, 2020). "It is unclear why there was not good concordance for FASN, GSK3b and NCad, but directional discordance between mRNA and protein for any given gene is not an unanticipated finding, and on an individual gene level, is more discordant in tumor versus cognate normal tissue." (PMID 31881020, 2019). "However, in cells with overexpression of GSK3β, an oncogenic pathway independent of β-catenin may become dominant and promote tumor development." (PMID 30275459, 2018). "The less effect of cimetidine and olanzapine (both repurposed, but not specific GSK3β inhibitors) on GBM cell proliferation at their limited dose ranges does not always make a denial of the solid evidence for the critical role of GSK3β in promoting proliferation of tumor cells including GBM." (PMID 28423558, 2017). "NTR1 antagonist SR48692 and special GSK3β phosphorylation inhibitor TWS119 were used to block the transduction of NTS signaling and the activation of Wnt/β-catenin pathway in NTS-treated Hep3Bwt cells and to validate whether NTS induces tumor EMT by activating the canonical Wnt/β-catenin pathway." (PMID 27611941, 2016). "GSK3B-53BP1 axis controls HR-mediated DSB repair and determines synthetic lethality response of tumor cells to PARP1 inhibition independent of BRCA1 status." (PMID 41243969, 2025). "This not only increases drug efflux but also activates the PI3K/AKT/GSK-3β pathway in the absence of PTEN and promotes tumour growth." (PMID 38889771, 2024). "Furthermore, Ctnnb1 expression was increased in tumours compared to both FL and RD livers and among the components of the β-catenin destruction complex, Axin1 and the known β-catenin target Axin2 was significantly upregulated, while Apc, Gsk3a and Gsk3b were not differentially expressed." (PMID 37907668, 2023).
tumor (continued). "The data from both the EL4 and B16 flank tumors demonstrate non-redundant activity of the GSK-3α and GSK-3β isoforms, with genetic inactivation of GSK-3β resulting in enhanced rejection of both tumor types in the flank." (PMID 34142056, 2021). "T cell distributions within the peribronchial regions (areas surrounding the tumors rather than within the tumor itself) were also examined revealing accumulations of CD4+ T cells in the double cKO and Gsk3a cKO but not the Gsk3b cKO mice." (PMID 34142056, 2021). "Additionally, the positive staining of Gsk3β detected by immunohistochemistry was apparently less in 8 of 13 miR-410high low-differentiated versus that was more in 7 of 11 miR-410low moderate-differentiated tumor tissues, compared with their respective non-cancerous tissues." (PMID 28076327, 2017). "The comparison of GSK3B and CTNNB1 expression levels between pre- and post-therapeutic tumour samples revealed no clear differences, whereas a significant increase in the expression of NOTCH2 was found." (PMID 22970250, 2012). "To evaluate whether FAK activity influences GSK3β, we treated ALK/MYCN tumor cells with or without the FAK inhibitor defactinib." (PMID 38451815, 2024). "However, we showed that CHIR-99021 acts specifically on HSCs in the tumor environment and exerts anti-fibrotic effects by regulating DNMT3B activity rather than GSK3β activity." (PMID 38168140, 2024). "In our study, overexpressed AQP9 reduced the levels of DVL2, p-GSK-3β, CyclinD1 and β-catenin, suggesting that AQP9 could be a novel tumor suppressor by suppressing Wnt/β-catenin signaling pathway." (PMID 31969493, 2020). "However, our data of Western blot showed that the phosphorylation of GSK-3β and STAT5a had no significant changes after ESCCAL_1 knockdown, suggesting that down-regulation of ESCCAL_1 inhibiting ESCC tumor growth involved in other signaling pathway." (PMID 29416654, 2018). "We firstly assayed and compared GSK-3β mRNA levels in 60 TTs(tumor tissues) and their matched NTTs(nontumorous tissues) by the way of RT-PCR assay, in which 50 of 60 (83.3%)specimens showed GSK-3β mRNA over-expression in HCC(tumor/nontumorous ratio>2.0)." (PMID 25157753, 2014). "Furthermore, treatment with a specific GSK-3β inhibitor BIO produced a concentration-dependent and significant decrease in tumour cell growth (P<0.001 vs non-treated group)." (PMID 22343623, 2012). "We show that the impact of GSK3B and CTNNB1 to this signature is not dependent on chemotherapy and more likely reflects a property of the primary tumour and our data further suggest, that in particular NOTCH2 might play a role for chemotherapy resistance in GC." (PMID 22970250, 2012).
cancer (961 papers, 2006 to 2026). A tumor composed of atypical neoplastic, often pleomorphic cells that invade other tissues. "Integrated multi-omics analysis of 31 malignancies revealed divergent dysregulation of GSK3 isoforms: GSK3α was upregulated in 19 solid tumors but suppressed in AML, while GSK3β was elevated in 23 cancers and high-risk AML subtypes (FAB-M0/M1, P = 0.0013)." (PMID 41915675, 2026). "The inactivation of GSK3β has been associated with boosting the effectiveness of cancer treatment drugs, and it also protects tissues from the harmful effects of traditional cancer treatments." (PMID 40072085, 2025). "Upregulated PD-L1 following irradiation in radioresistant cancer cells enhanced its association with GSK3β, leading to its inactivation by phosphorylation and subsequent increase in cell proliferation and survival." (PMID 40427133, 2025). "CD36-induced metastasis is known to be linked to the glucose and lipid metabolism of cancer cells and mediated through the GSK-3β/β-catenin signaling pathway." (PMID 39752516, 2025). "We therefore also analysed protein expression of GSK3b, which is a well‐known negative regulator of glucose homeostasis, and changes in protein expression have been associated with cancer." (PMID 40874518, 2025). "This modification results in GSK3β inactivation via proteasomal degradation, a process implicated in various pathological conditions, including cancer." (PMID 39744435, 2025). "Dysregulation of GSK‐3β has been implicated in several pathologies including cancer, neurodegenerative, and neuropsychiatric disorders." (PMID 40676806, 2025). "GSK3B dysregulation is linked to certain cancers, lipid metabolic disorders, and Alzheimer's disease." (PMID 39166606, 2024). "Overall, our results introduce cephalosporins as GSK3β covalent inhibitors, providing evidence of the mechanism of action underlying their benefits in cancer and AD." (PMID 37057264, 2023). "GSK-3β is associated with a variety of diseases, including inflammation, neurodegenerative diseases, diabetes, and cancer." (PMID 35836256, 2022). "Nuclear localization of GSK-3β is associated with a worse outcome and drug resistance in cancer, and the inhibition of GSK-3β activation decreases its nuclear accumulation." (PMID 36430630, 2022). "Accumulating evidence suggests that GSK3β is a crucial regulator of the oxidative stress response associated with the occurrence and development of cancer." (PMID 35350242, 2022). "Here, the changes of three key molecules (IRS1, JUN and GSK3B) in the cancer-associated pathways were verified by real-time PCR and Western blotting." (PMID 36446361, 2022). "Cyclin D1 activity is normally intensified in cancer; therefore, cancers showing overexpression of cyclin D1 are susceptible to GSK-3β activation." (PMID 35807651, 2022). "In fact, recent studies within cancer cell lines have implicated GSK3β directly in the phosphorylation of 4EBP1." (PMID 34359954, 2021). "GSK3B is implicated in different diseases including inflammation, neurodegenerative disease, diabetes and cancers." (PMID 34065438, 2021). "Glycogen synthase kinase-3β (GSK3β) controls many physiological pathways, and is implicated in many diseases including Alzheimer’s and several cancers." (PMID 33110096, 2020). "The kinase activity of GSK3β is implicated in many cancers and in neurodegenerative diseases, including Alzheimer’s and Parkinson’s diseases." (PMID 33110096, 2020). "GSK3β inhibition via the high expression of p-GSK3βser9 has been shown to cause resistance to rapamycin in cancer cell lines." (PMID 33145347, 2020). "The dysregulation of GSK-3β has been implicated in various human diseases, such as diabetes, cancer, bipolar mood disorder, liver diseases, and neurodegenerative diseases." (PMID 32526891, 2020). "Induction of cyclin D1 degradation and triggered dephosphorylation of GSK3β, which caused G1 arrest and resulted in inhibiting proliferation of cancer cells." (PMID 33014527, 2020).